CDK12 (cyclin dependent kinase 12)
Diseases named in the same sentence as CDK12 in open-access papers (continued):
Sharing a sentence is not in itself a finding about the gene and the disease.
tumor (continued). "However, when compared to other HR-deficient mCRPCs, the CDK12-abberant tumours were found to be transcriptionally, genetically and phenotypically different and displayed more aggressive clinical behaviour (including higher Gleason scores at presentation, a shorter time to metastasis and CRPC)." (PMID 34316683, 2020). "CDK12 knockdown combined with sorafenib suppresses tumor growth by over 70% and reduces expression of EGFR, c-MET, and DDR1, key drivers of HCC progression." (PMID 41491919, 2026). "Analysis of tumor versus normal tissue shows that CDK12 and CDK13 are frequently upregulated across multiple cancer types." (PMID 41491919, 2026). "In tumor cells, aberrant CDK12/13 activity contributes to induction of alternative splicing that supports oncogenic signaling and therapy resistance." (PMID 41491919, 2026). "Large-scale CRISPR dependency screens confirm that numerous tumor cell lines display strong dependence on CDK12/13." (PMID 41491919, 2026). "Functionally, CDK12 promotes tumor initiation, self-renewal, and trastuzumab resistance through activation of WNT/β-catenin and IRS1–ErbB–PI3K–AKT signaling." (PMID 41491919, 2026). "Among the eight significant mutated genes, CDK12, CTNNB1, and MLH1 were tested in both tumor and blood, whereas CTCF, IGF1R, IKBKE, QKI, and TIPARP were only tested in tDNA." (PMID 40227722, 2025). "Increased tumor growth, cell mobility, spheroid formation, and EMT are all associated with elevated CDK12 levels, and these factors all aid in the advancement of cancer." (PMID 40361480, 2025). "GBM12 xenografts with CDK12 knockdown showed significantly reduced tumor growth by MRI and prolonged survival compared with controls." (PMID 40996961, 2025). "The promising anti-cancer effects of THZ1 and THZ531 in several tumours has paved the ground for the developing novel CDK12/13 inhibitors." (PMID 39533070, 2025). "CDK12 is recognized as a key regulator of the cell cycle, and it has been described as a marker of tumor progression in BC." (PMID 40136626, 2025). "Responders were enriched for MMR-d, BRCA1/2 loss, high TIL density, CDK12 loss, ATM or CHD1 alterations, underscoring the predictive value of a broad tumor-based immunogenic signature." (PMID 40806607, 2025). "Using novel mouse models, we establish cyclin-dependent kinase 12 (CDK12) as a bona fide tumor suppressor gene in tubo-ovarian high-grade serous carcinoma, demonstrating that its loss drives increased tumorigenesis and progression." (PMID 40504161, 2025). "CDK12 SNV, deleterious mt SNVs and severe chromothripsis were linked with overall survival in stage 3 tumours alone, which is consistent with effects that are independent of stage at diagnosis." (PMID 40593568, 2025). "We, thus, depleted Cdk12, Cdk13, or both in tumor cells with siRNAs and assessed R-loops with the S9.6 antibody, the specificity of which was confirmed using RNase H treatment." (PMID 40955658, 2025). "CDK12/13 degradation delayed tumor growth and synergized with anti–PD-1 therapy in syngeneic tumor models, enhancing STING activity and promoting CD8+ T cell infiltration and activation within tumors." (PMID 40955658, 2025). "In our system, coablation of Cdk12 (m-sgPRN;Cdk12KO) recapitulated hallmark features of HGSC, while accelerating tumor progression and reducing survival." (PMID 40504161, 2025). "Strikingly, combined CDK12 inhibition and temozolomide treatment led to complete tumor eradication in all animals tested." (PMID 40996961, 2025).
tumor (continued). "To date, preclinical studies have highlighted the efficacy of THZ1 and THZ531, which are potent CDK12/13 inhibitors, against several types of tumours." (PMID 39533070, 2025). "CDK12 can act as a tumour suppressor by maintaining genomic stability via regulating DNA damage response (DDR) genes." (PMID 40163908, 2025). "CDK12 directly interacts with and regulates GSK3β, which in turn influences tumor metabolism and growth." (PMID 40996961, 2025). "Although Cdk12/13 depletion exerted a direct tumor inhibitory effect in immunodeficient mice, consistent with previous studies, the tumor growth delay was significantly more pronounced in immunocompetent mice." (PMID 40955658, 2025). "Genetic or pharmacologic inactivation of CDK12 impaired tumor growth in patient-derived xenograft (PDX) models and enhanced the efficacy of temozolomide." (PMID 40996961, 2025). "We further explored single-cell sequencing data from ICB-treated cohorts to specifically evaluate the expression of CDK12/13 in tumor cells." (PMID 40955658, 2025). "Together, our data show that targeting CDK12/13 delays tumor growth and enhances response to anti–PD-1 across various preclinical models." (PMID 40955658, 2025). "Together, these data demonstrate that Cdk12 is a bona fide tumor suppressor gene in tubo-ovarian HGSC—its loss promoting tumorigenesis, tumor progression, and DNA damage (in some cases associated with a tandem duplicator phenotype)." (PMID 40504161, 2025). "develop YJ1206, an orally bioavailable degrader that exhibits high specificity in degrading CDK12/13 and demonstrates robust anti-tumor activity in vivo." (PMID 39353441, 2024). "Together, these data identify CDK12 as a bona fide tumor suppressor gene with impact on tumor progression and lends support to paralog-based synthetic lethality as a promising strategy for treating CDK12-mutant mCRPC." (PMID 38562774, 2024). "Cdk12 is a tumor suppressor gene responsible for mitigating AR/Myc hypertranscription and TRC-mediated DNA damage." (PMID 39368479, 2024). "Compared to the control xenograft tumours, IACS‐010759 more effectively inhibited the growth of CDK12 knockout xenograft tumours." (PMID 38736108, 2024). "At the same time, AS deregulation increases the sensitivity of CRPC, as well as several other tumour types, to the anti-tumoral activity of inhibitors of the splicing process and of transcriptional kinases, such as CDK12/13." (PMID 38413979, 2024). "CDK12 has been found to drive and maintain the growth of cancer cells in a variety of tumours by regulating multiple signalling pathways, including the WNT/β-catenin pathway, MAPK pathway, NF-κB pathway, and DNA damage repair (DDR) pathway." (PMID 38503865, 2024). "Tumor cell proliferation was primarily attributed to activation of the ERBB2 and CDK12 pathways; lung and lymph node specific mutations were also detected." (PMID 38539567, 2024). "Our combined analysis of CDK12-defective public domain data and our cohort study indicate that low expression of MHC in primary tumor clones are often linked to structural alterations, such as somatic CN-LOH and LOH subclonal genomic alterations." (PMID 38704603, 2024). "To further investigate the mechanism by which CDK12 regulates tumour metabolism, we conducted RNA sequencing on CDK12 control and knockout C4‐2 cells." (PMID 38736108, 2024). "Established early oncogenic driver alterations including ERG gene fusions as well as FOXA1, CDK12, and SPOP mutations were typically present in both the primary tumor and LN metastatic foci." (PMID 38773085, 2024).
tumor (continued). "As outcomes of CDK12 alterations are context dependent, CDK12 has been reported to function as a tumor suppressor and as an oncogene." (PMID 37811895, 2023). "This signature, together with high expression of ERBB2 and co-amplified CDK12 in organoids, recapitulated the genomic changes from the patient’s original tumor." (PMID 37508518, 2023). "We only observed a single tumour with biallelic LOF of CDK12 in PCAWG, but the predictive model was able to correctly identify this tumour, and reached a PR-AUC-E of 0.99 in the PCAWG data set." (PMID 36883553, 2023). "As a first step toward gaining an understanding of the molecular mechanism by which CDK12/13 inhibitors inhibit osimertinib-resistant tumor growth, we investigated the effect of these drugs on cell-cycle progression." (PMID 37190191, 2023). "Specifically, we found that the GILncSig was significantly linked to the tumor mutation phenotype and to PTEN, CDK12, SPOP, and TMPRSS2 expression in PCa, all of which are vital signs of genomic instability." (PMID 35860569, 2022). "Mirroring the data obtained in CDK12-OE vs. control MCF10A cells, GSEA showed enrichment of glycolysis and SGOC network genes in the transcriptomic profiles of CDK12-KI/PyMT vs. WT/PyMT tumor cells." (PMID 35550508, 2022). "Parallelly, attenuated distribution of tumour foci across the intestine and decreased metastatic foci in the liver were observed in nude mice orthotopically implanted with CDK12‐depleted HCT116 cells compared with mice bearing Scramble control cells." (PMID 36254394, 2022). "Both CDK12-KI/PyMT and CDK12-KI/NeuN female mice showed significantly increased tumor multiplicity and average tumor size, and reduced tumor-free survival rate, compared to their respective WT/PyMT and WT/NeuN controls." (PMID 35550508, 2022). "We transplanted parental and CDK12 KO cells in nude mice and examined their tumor take and tumor growth." (PMID 35912188, 2022). "Of importantly, increased apoptosis was also detected by IHC staining with antibody against active caspase‐3 in SR‐4835‐administered HCT116 xenografts or CDK12‐silenced xenograft tumours." (PMID 36254394, 2022). "THZ1 is a highly selective covalent inhibitor of CDK7 with anti-tumor activity against multiple different types of cancer, but also inhibits CDK12 and CDK13 at higher concentrations." (PMID 36279270, 2022). "Whole-genome sequencing was performed on the biopsied metastatic lymph node in search for another possible treatment and it revealed that the tumor had WGD and CDK12 mutation." (PMID 35183184, 2022). "More importantly, the in vivo anti‐tumour activity of SR‐4835 was also observed in mice subcutaneously implanted with CDK12‐silenced HCT116 cells." (PMID 36254394, 2022). "Of note, the reduction in the survival rate was even more evident in CDK12-KI/PyMT vs. WT/PyMT male mice, likely due to the attenuation of the difference in female mice because of their very accelerated kinetics of tumor progression." (PMID 35550508, 2022). "We realize that all the data here rely on only one clone, but nevertheless all are compatible with the known function of CDK12 and support its role for survival in tumor cells too." (PMID 35912188, 2022). "In the entire cohort of 4994 patients, 0.5% were identified with CDK12 alterations on primary tumor testing and 0.26% on metastasis testing." (PMID 34898046, 2022). "An increasing number of studies point to the role of CDK12, in cell function and cancer, as an effective strategy to inhibit tumor growth, and its potential clinical use as a biomarker." (PMID 33805800, 2021). "Gene amplifications of CCND1, CDK12, CCNE1, and ERBB2 were identified in patients with low tumor mutational burden." (PMID 34068652, 2021). "This suggests an exciting possibility of targeting these oncogenic pathways by CDK12 inhibition in various types of tumours." (PMID 34316683, 2020).
tumor (continued). "It was demonstrated that chemical inhibition of CDK12 reduced tumor growth with the concurrent abrogation of MYC expression in patient-derived xenograft experiments." (PMID 32451425, 2020). "Through a silicon assay, we found that CDK12 participated in the c-myc/β-catenin pathway to promote tumor progression." (PMID 32489449, 2020). "In patient 9, SMO, NTRK3, IDH2, IGF1R, and CDK12 were also amplified in tumour #1 in addition to ERBB2 amplification." (PMID 31929516, 2020). "Increasing knowledge of CDK12 aberrations in tumours, the roles of CDK12 in various cellular processes and the recent availability of CDK12 inhibitors have contributed to this exciting development." (PMID 34316683, 2020). "CDK12 is both a tumour suppressor and oncogene, and the functional outcomes of CDK12 aberrations are case and context dependent." (PMID 34316683, 2020). "CDK12 promotes tumor initiation through regulating cancer stem cells (CSCs) or affecting the genes which are necessary to activate downstream pathways such as ErbB-PI3K-AKT (Protein Kinase B) or WNT-signaling cascades." (PMID 32570740, 2020). "Our data demonstrated that inhibiting CDK12 expression in vivo and in vitro significantly suppressed cancer cell proliferation and tumor weights." (PMID 32489449, 2020). "Tumor tissues were also subjected to H&E staining and IHC staining with CDK12, Ki67, phospho-MEK and phospho-ERK." (PMID 32483448, 2020). "The mutations of CDK12 in high-grade serous ovarian cancer (HGSOC) are mostly homozygous, indicating that they are driver mutations of a tumour suppressor." (PMID 34316683, 2020). "Median scores of CDK12 in tumor tissues and non-tumor tissues were 6 (range: 3-8) and 5 (range: 0-8), respectively." (PMID 31523177, 2019). "Positive correlations were found between CDK12 expression and number of CD8+ cells in tumor tissues, as well as between CDK12 and CCL21 mRNA expression." (PMID 31523177, 2019). "Staining scores of CDK12 in tumor tissues were significantly higher than those in paired non-tumor tissues (P<0.001)." (PMID 31523177, 2019). "Number of CD8+ cells was positively correlated with CDK12 expression score in tumor tissues (r=0.243, P=0.024)." (PMID 31523177, 2019). "We hope that future use of the CDK12as cell line will provide a better understanding of these and other CDK12-dependent events, elucidating specific in vivo functions of CDK12 and providing new insights into its role as a tumor suppressor." (PMID 31652541, 2019). "Given this potentially actionable molecular subtype, we sought to determine the prevalence of monoallelic and biallelic CDK12 alterations across tumor types." (PMID 31360735, 2019). "Similar with IHC staining, mRNA expression of CDK12 in tumor tissues was significantly higher than that in non-tumor tissues (4.04±3.25 vs. 1.56±0.84, P=0.009)." (PMID 31523177, 2019). "Human CDK12, a tumor suppressor for ovarian and other cancers, is the catalytic subunit of the protein kinase complex CDK12/CyclinK." (PMID 31652541, 2019). "The data, if confirmed in other cohorts of ovarian patients, will allow the identification of a subgroup of patients (high level of CDK12 mRNA and residual tumor < 2 cm) to be potentially enrolled in clinical trials with alternative therapies." (PMID 29872499, 2018). "This notion predicts that tumor cells overexpressing cyclin E1 should need high level of CDK12 and/or cyclin K to sustain high rate of proliferation." (PMID 29760377, 2018).
tumor (continued). "High CDK12 activity would therefore accelerate tumor progression and therapy resistance, paradoxically to its proposed role as a tumor suppressor." (PMID 29090014, 2017). "The therapeutic effect of olaparib on CDK12-silenced tumor cells was confirmed in vivo in xenograft experiments." (PMID 29090014, 2017). "For 70 of the 240 analyzed patients (29.1%) we were able to determine the expression of CDK12 mRNA in tumor." (PMID 27905519, 2016). "CDK12 A/A, A/G genotypes statistically correlated with both low grade (p = 0.0028) and residual tumor <2 cm (p = 0.032)." (PMID 27905519, 2016). "In many cancers, elevated CDK12/13 activity is a key driver of tumor progression." (PMID 41491919, 2026). "Consequently, CDK12/13 inhibition sensitizes tumor cells to PARP inhibitors and DNA-damaging agents, effectively expanding the utility of HR-directed therapies." (PMID 41491919, 2026). "Pharmacologic inhibition of CDK12 with THZ-531 reverses this transcriptional balance, downregulating DDR and cell-cycle genes while upregulating AP-1 and NF-κB targets, thereby promoting apoptosis and loss of tumor viability." (PMID 41491919, 2026). "Previous speculation on CDK12 tumor suppressor function focused on its role in maintaining genomic integrity." (PMID 40504161, 2025). "Depending on the tumour context, CDK12 might contribute to the oncogenic phenotype by favouring the translation of oncogenic proteins, while guaranteeing genome stability by ensuring the proper translation of mitosis-related proteins." (PMID 39533070, 2025). "To determine whether Cdk12 functioned as a tubo-ovarian HGSC tumor suppressor, we developed a novel transgenic mouse line in which the impact of its loss on tumor progression could be analyzed." (PMID 40504161, 2025). "Collectively, these findings show that targeting CDK12/13 activates STING signaling in tumor cells." (PMID 40955658, 2025). "While the majority of the mCRPC cohorts were comprised of single tumors from an individual patient, the UW autopsy study included three patients with CDK12BAL where multiple tumors were sampled, allowing for assessments of tumor heterogeneity with respect to CDK12 events." (PMID 39071291, 2025). "We next sought to determine the gene composition within tandem duplications (TDs) to assess whether consistent oncogenic drivers or tumor suppressor mechanisms accompanied CDK12 inactivation." (PMID 39071291, 2025). "Furthermore, Cdk12/13 depletion significantly delayed tumor growth (bottom), extending the time to endpoint from 13 days in controls to 29 days after treatment." (PMID 40955658, 2025). "Interestingly, in various cancer types, CDK12 exhibits both tumorigenic and tumor-suppressive actions." (PMID 40361480, 2025). "We depleted Cdk12, Cdk13, or both in the Myc-CaP tumor model (top)." (PMID 40955658, 2025). "Cyclin-dependent kinase 12 (CDK12) inactivation—frequently observed in human HGSC—is associated with poorer outcomes, DNA damage accumulation (including tandem duplications), and increased tumor immunogenicity." (PMID 40504161, 2025). "CDK12 inactivation is known to increase the immunogenicity of tumor cells." (PMID 38704603, 2024). "The tumor suppressor function of CDK12 has been attributed to its regulation of DDR genes." (PMID 39368479, 2024).